MAPK14 (mitogen-activated protein kinase 14)
Diseases named in the same sentence as MAPK14 in open-access papers (continued):
Sharing a sentence is not in itself a finding about the gene and the disease.
depression (9 papers, 2018 to 2025). "In this module, ADCYAP1R1, PRKACA, MAPK8, MAPK14, GRIA1, and FOS are both targeted genes of CGFC and pathogenic genes of depression; RHOA is a specific targeted gene of CGFC, and most of these genes are related to the pathogenesis or treatment of depression." (PMID 34867413, 2021). "In this study, the present findings reveals that the expressions of ULK1, MAPK14, WIPI1, and DUSP1 were associated with the immune system, thereby participated in the pathogenesis of depression and could provide potential targets for future treatments." (PMID 41311024, 2025). "Studies have also confirmed that MAPK14 may play an important role in depression." (PMID 37012370, 2023). "A MAPK14 inhibitor has been tried for treatment of major depression but did not demonstrate consistently significant effects on symptom rating scales compared with placebo at the single dose tested." (PMID 28688579, 2018).
gastric cancer (9 papers, 2021 to 2025). A primary or metastatic malignant neoplasm involving the stomach. "By integrating the final data, SOD2, sulfiredoxin 1 (SRXN1), neurogenic locus notch homolog protein 1 (NOTCH1), and mitogen-activated protein kinase 14 (MAPK14) were predicted to be the target genes for the anti-gastric cancer effects of WNG." (PMID 39252074, 2024). "MAPK14, as one of p38 proteins, was found to be a potential biomarker for advanced gastric cancer as well as a pharmacological target." (PMID 37537191, 2023). "In present work, TCGA database results showed MAPK14 was significantly upregulated in gastric cancer samples compared with normal samples, especially in advanced stages (stage 3 and 4)." (PMID 37537191, 2023). "Mitogen-activated protein kinase 14 (MAPK14, aka p38) contributes to aggressive disease in hepatocellular carcinoma, gastric cancer, and renal cell carcinoma." (PMID 35158795, 2022). "Molecular docking showed that IH might affect the function of MAPK14 protein, and then the underlying action mechanisms of IH on STAD were experimentally validated using human gastric cancer cell line, HGC-27 cells." (PMID 37537191, 2023). "Similarly, using bioinformatics analysis, another concurrent study has shown that a G2/M checkpoint-related signature composed of five genes (MARCKS, CCNF, MAPK14, INCENP, and CHAF1A) was connected with the prognosis of gastric cancer (GC) patients." (PMID 35419294, 2022).
injury (9 papers, 2017 to 2025). Damage inflicted on the body as the direct or indirect result of an external force, with or without disruption of structural continuity. "Consistently, the constructing PPI network in our result provides evidence that MAPK14 (p38α) activation was shown to make greater contributions to TLR4-mediated MMP-9-induced post-aSAH brain injury." (PMID 36438795, 2022). "MAPK14 (Mitogen-activated protein kinase 14) could activate MAPK signaling pathway to aggravate acute lung injury (ALI) in septic shock mice." (PMID 33949285, 2021). "Considering the fact that one miRNA can regulate multiple target genes, and several miRNAs can regulate the single gene to exert its effect, the modulation of MAPK14 and STAT3 during INH-induced liver injury may be conceivable." (PMID 29554950, 2018).
Obesity (9 papers, 2014 to 2022). Accumulation of substantial excess body fat. "In visceral fat and sWAT from individuals with obesity and those without obesity, we found that expression of Mapk14 correlated positively with the levels of Ucp1." (PMID 29979672, 2018). "Using 2 cohorts for visceral fat and subcutaneous fat (sWAT) of adult patients with 80 and 170 samples, respectively, we found that the expression of p38α (Mapk14) in visceral fat and sWAT from individuals with obesity was reduced compared with those without obesity." (PMID 29979672, 2018).
Arthritis (8 papers, 2007 to 2022). Inflammation of a joint. "Mapk14, a candidate gene for locus 8 and also called p38 mitogen-activated protein kinase (MAPK) alpha, regulates the production of arthritis-essential cytokines, such as tumour necrosis factor and interleukin-1." (PMID 17244351, 2007).
asthma (8 papers, 2012 to 2025). "To explore the role of DC-intrinsic p38α signaling in asthma pathogenesis, we generated mice with specific p38α deletion in DCs by crossing Mapk14 (encoding p38α) fl/fl mice with CD11c-Cre mice, referred to as p38αΔDC mice." (PMID 35551270, 2022). "A total of 129 overlapping targets between the PEF and asthma were obtained by jvenn online tools, among which five targets might play important roles: MAPK14, JUN, STAT3, MAPK3, and MAPK1." (PMID 36172200, 2022). "In this study, the IL-17 signaling pathway was found by the KEGG enrichment analysis to be an important pathway by which the PEF counteracted asthma, and 15 targets are involved (including the core targets MAPK1, MAPK14, MAPK3, and JUN)." (PMID 36172200, 2022). "The top 10 highest degree of targets were EGFR, JAK1/2, MAPK14, VEGF, SRC, mTOR, PI3K, and GSK3B, which might be the critical targets of HHAE for the treatment of asthma." (PMID 36408342, 2022).
chronic obstructive pulmonary disease (8 papers, 2013 to 2025). A chronic and progressive lung disorder characterized by the loss of elasticity of the bronchial tree and the air sacs, destruction of the air sacs wall, thickening of the bronchial wall, and mucous accumulation in the bronchial tree. "PGF and its downstream MAPK8 and MAPK14 signaling pathways are potential therapeutic targets for the treatment of emphysema and chronic obstructive pulmonary disease (COPD)." (PMID 28642633, 2017). "Some studies have shown that activated MAPK14 is highly expressed in the alveoli of smokers with chronic obstructive pulmonary disease (COPD)." (PMID 36918848, 2023). "A total of 379 targets related to BHC and 7391 targets related to COPD were obtained, including 313 potential targets of BHC in treating chronic obstructive pulmonary disease, with JUN, AKT1, TNF, IL6, EGFR, MAPK1, and MAPK14 as the core targets." (PMID 36523421, 2022).
heart failure (8 papers, 2013 to 2023). Inability of the heart to pump blood at an adequate rate to meet tissue metabolic requirements. "Interestingly, both FOXO1 and MAPK14—another important node in our network—were also implicated in the development of heart failure, therefore the identified targets may reflect key regulating mechanisms in both atherosclerotic disease and heart failure." (PMID 28293796, 2017). "An increase in MAPK14 activity was also observed in animal models of heart failure and myocardial biopsies of heart failure patients." (PMID 37959722, 2023).
liver cancer (8 papers, 2010 to 2025). An epithelial or non-epithelial malignant neoplasm that arises from the liver. "Furthermore, a pooled shRNA screen conducted to identify target genes whose inhibition increases the therapeutic efficacy of Sorafenib identified MAPK14-dependent activation as a key mechanism of Sorafenib resistance in mouse and human liver cancer." (PMID 25957784, 2015). "MiR-622 as well as MAPK14 and ATF2 represent promising potential therapeutic targets in liver cancer." (PMID 33803354, 2021). "Subsequently, MAPK14 and ATF2 were both identified as novel, direct target genes of miR-622 in liver cancer." (PMID 33803354, 2021). "Combined upregulation of MAPK14 and ATF2 in liver cancer cells was also determined on the protein level applying Western blot analysis." (PMID 33803354, 2021). "Together, these data suggested a combined regulatory mechanism for MAPK14 and ATF2 overexpression in liver cancer." (PMID 33803354, 2021). "In conclusion, combinations of specific MAPK14- and ATF2-inhibitors might outline a synergistic therapeutic approach in (liver) cancer." (PMID 33803354, 2021).
myocardial infarction (8 papers, 2017 to 2024). Gross necrosis of the myocardium, as a result of interruption of the blood supply to the area, as in coronary thrombosis. "Mitogen-Activated Protein Kinase 14 (MAPK14), encoding the most abundant α-isoform of p38 MAPK in human cardiac tissue, has been found to aggravate myocardial infarction during ischemi." (PMID 38956669, 2024).
neuroblastoma (8 papers, 2008 to 2022). Neuroblastoma (NB) is the most common solid, extracranial childhood tumor. "In addition, MAPK14 (Mitogen-activated protein kinase 14), which promotes differentiation of neuroblastoma cells into neurons mediated by adrenergic receptors and MAPK pathway, was also up-regulated upon exposure to both hNET-homing peptides." (PMID 32660596, 2020).
non-small cell lung carcinoma (8 papers, 2016 to 2025). A group of at least three distinct histological types of lung cancer, including non-small cell squamous cell carcinoma, adenocarcinoma, and large cell carcinoma. "MAPK14 was previously reported to predict the risk, chemotherapy toxicity, and tumor progression in non-small cell lung cancer and was identified as a critical target of various anti-tumor herbal compounds, such as Andrographis and Polygonatum cyrtonema Hua." (PMID 40500789, 2025). "In non-small-cell lung cancer, there is overexpression of elements, including MAPK14, in the MAPK signaling pathway, thereby highlighting the need to inhibit the enzyme." (PMID 38727308, 2024).
osteoarthritis (8 papers, 2021 to 2025). A noninflammatory degenerative joint disease occurring chiefly in older persons, characterized by degeneration of the articular cartilage, hypertrophy of bone at the margins and changes in the synovial membrane. "The high expression of MAPK-14 works as a promoter of chondrocytes death and an important signal of the osteoarthritis process." (PMID 33520453, 2021). "Research on osteoarthritis (OA) has revealed that the expression of growth differentiation factor 15 (GDF15) may trigger cellular senescence in cartilage cells by activating MAPK14." (PMID 41170318, 2025). "Within tier 1, ten candidates have previously been studied in clinical trials of efficacy or in cohort studies of osteoarthritis (six arising from new signals: PPARD, NR3C1, VDR, MAPK14, IGF1R, and CHST3)." (PMID 34450027, 2021). "Although there is currently no research on the association between GDF15 and MAPK14 in renal disease, a study has demonstrated the presence of the GDF15/MAPK14 axis in osteoarthritis." (PMID 40854626, 2025). "The MAPK14 antagonist PH-797804 has been studied in a phase 2 clinical trial to examine the pain relief of PH-797804 alone or with naproxen in subjects with osteoarthritis of the knee (NCT01102660), although we are not aware of any trial results reporting in PubMed or on ClinicalTrials.gov." (PMID 34450027, 2021).
viral infections (8 papers, 2009 to 2024). "MAPK1, MAPK3, MAPK8 and MAPK14 can be activated by stimulating phosphorylation during changes in the internal environment, such as osmotic pressure changes, oxidative stress, inflammatory factors and viral infection." (PMID 35165507, 2022). "MAPK14 could be activated by inflammatory cytokines induced by virus infections and subsequently activate the downstream effectors that participate in the induction of IFN-dependent gene transcription." (PMID 19671175, 2009). "Curiously, the downregulation of MAPK14 in our study could represent a protective mechanism operated by SARS-CoV-2 to avoid apoptosis, as observed in other viral infections." (PMID 34948400, 2021).
influenza (7 papers, 2011 to 2024). An acute viral infection of the respiratory tract, occurring in isolated cases, in epidemics, or in pandemics; it is caused by serologically different strains of viruses (influenzaviruses) designated A, B, and C, has a 3-day incubation period, and usually lasts for 3 to 10 days. "Studies have shown that the activation of the MAPK14 protein is a key to elevated circulating pro-inflammatory cytokine levels in patients with severe influenza." (PMID 36452894, 2022). "Bioinformatics analysis predicted that six active compounds of CSTRG including quercetin, kaempferol, luteolin, beta-sitosterol, sitosterol, and stigmasterol could contribute to the anti-influenza activity through regulating the TRAF6/MAPK14 axis." (PMID 36452894, 2022).
ischemic stroke (7 papers, 2019 to 2024). A stroke disorder caused by obstruction of blood flow to the brain, due to thrombotic (local blood clot formation) or embolic (due to a blood clot or other material traveling from another site) event. "Some studies have reported that MAPK14 can be used as a marker of cardiogenic stroke, and it has also been demonstrated from large data of ischemic stroke-related LncRNA that MAPK14 is a key gene in ischemic stroke, but there are fewer relevant animal experimental studies." (PMID 34603472, 2021). "Furthermore, through network pharmacology and molecular docking, four core targets (MAPK3, TNF-α, MAPK14, and JNK) closely related to RPR’s treatment of ischemic stroke were identified, exhibiting strong affinity with two key active components of RPR: albiflorin (AF) and β-sitosterol (BSS)." (PMID 39771032, 2024).
leukemia (7 papers, 2010 to 2026). A malignant (clonal) hematologic disorder, involving hematopoietic stem cells and characterized by the presence of primitive or atypical myeloid or lymphoid cells in the bone marrow and the blood. "Proteomics reveal that MA191 also degrades MAPK14 (p38α), a kinase upregulated in leukemia, in addition to FLT3." (PMID 42198431, 2026). "In limited studies, stilbenes were proved to be highly related to targets of leukemia treatments, for example, pterostilbene, a 3′, 5′-dimethoxy-resveratrol interacted with 25 targets, including MAPK14, CDK2, and HSP90AA1, which are highly related to leukemia." (PMID 32104190, 2020).
myocardial ischemia (7 papers, 2010 to 2025). A disorder of cardiac function caused by insufficient blood flow to the muscle tissue of the heart. "During myocardial ischemia, MAPK14 is found to contribute to infarction, and short-term intraischemic inhibition of this MAPK14 in the intact heart reduces infarction." (PMID 31269974, 2019). "Inhibiting MAPK14 (p38α) diminishes cardiac damage in myocardial ischemia." (PMID 30135318, 2018).
pneumonia (7 papers, 2020 to 2025). An acute, acute and chronic, or chronic inflammation focally or diffusely affecting the lung parenchyma, caused by an infection in one or both of the lungs (by bacteria, viruses, fungi, or mycoplasma.). "In particular, it has been reported that USP7-dependent mitogen-activated protein kinase 14 (MAPK14) aggravates the progression of pneumonia." (PMID 40121492, 2025). "As previously documented, USP7 interacted with MAPK14, thereby playing a role in the regulatory mechanisms of esculin in the context of LPS-induced pneumonia." (PMID 40121492, 2025). "MAPK14 makes a vital regulatory role in various diseases, including pneumonia and acute lung injury, and inhibition of this pathway can alleviate inflammatory responses and oxidative stress levels in disease states." (PMID 38875180, 2024). "Compared with the model group, isorhamnetin reduced the protein expressions of SYK, IL-6, MAPK14, MAPK8, TNF-α, AKT, p-Akt, PIK3CA, EGFR and IL-1β in lung tissues of pneumonia mice." (PMID 36506534, 2022).
psoriasis (7 papers, 2020 to 2025). An autoimmune condition characterized by red, well-delineated plaques with silvery scales that are usually on the extensor surfaces and scalp. "Network pharmacology analysis showed that 20 transdermal constituents were associated with potential therapeutic targets for psoriasis, including TNF, MMP9, TLR4, ICAM1, EGFR, and MAPK14." (PMID 41012530, 2025). "It should be noted however, that while we reported similarly lowered MAPK14 levels in the case of inflammatory skin disease, vitiligo, its expression in psoriasis has been found to be elevated according to preceding studies by other authors." (PMID 34884858, 2021). "Additionally, proteins such as MAPK3, MAPK14, JAK2, and STAT1 were identified as having a direct impact on psoriasis-related disease proteins." (PMID 39590306, 2024). "MAPK14 mRNA expression was 9.0-fold lower (p < 0.001) in the lesional skin of psoriasis patients and 8.6-fold lower (p < 0.001) in psoriasis non-lesional skin than in the skin of healthy control subjects." (PMID 34884858, 2021). "Among all the targets, the top three were PTGS2, MAPK14, and NOS3 in terms of Degree, and all of them have been demonstrated to play important roles in the pathogenesis of psoriasis, such as inflammatory infiltration, abnormal differentiation of keratinocytes, and oxidative stress injury." (PMID 32655662, 2020). "In psoriasis uninvolved skin, positive correlations were found between the expression levels of CREB1 and LEF1 (r = 0.66, p < 0.05), USF1 and PNOC (r = 0.81, p < 0.05), MITF and ATRN (r = 0.58, p < 0.05), MITF and NURR1 (r = 0.56, p < 0.05) and MITF and MAPK14 (r = 0.75, p < 0.01)." (PMID 34884858, 2021). "Therefore, consistent with the discussion we propose that MAPKs (MAPK13 and MAPK14) and genes for AP-1 (FOSL1 and FOS) identified from sensitivity analysis of psoriasis are significant genes that might lead psoriasis towards cancer." (PMID 34267747, 2021).
diabetic nephropathy (6 papers, 2012 to 2022). "Meanwhile, the candidate gene analysis demonstrated a strong association for diabetic neuropathy (MAPK14: rs3761980, rs80028505), and diabetic nephropathy (APOL1: rs136161), proving the contribution of these risk loci in the pathogenesis of diabetic complications across various populations." (PMID 33430853, 2021). "By applying the targeted approach of previously reported susceptibility loci we managed to replicate three associations: MAPK14 (rs3761980, rs80028505) and diabetic neuropathy, APOL1 (rs136161) and diabetic nephropathy." (PMID 33430853, 2021). "By applying the targeted approach we managed to replicate two significant associations for diabetic neuropathy rs3761980 and rs80028505, both mapping to MAPK14 loci and one significant hit (rs136161, APOL1) for diabetic nephropathy in our study cohort." (PMID 33430853, 2021).